ASAH1 (N-acylsphingosine amidohydrolase 1)
Diseases named in the same sentence as ASAH1 in open-access papers (continued):
Sharing a sentence is not in itself a finding about the gene and the disease.
Insulin resistance (5 papers, 2019 to 2025). Increased resistance towards insulin, that is, diminished effectiveness of insulin in reducing blood glucose levels. "Mitochondrial overexpression of ASAH1 protects against insulin resistance and increases coenzyme Q (CoQ) levels in L6 myotubes." (PMID 38149844, 2023). "In turn, thermogenic regulation is impaired when ceramide degradation is inhibited through BAT-specific deletion of acid CDase (Asah1), exacerbating obesity, hepatic steatosis, and insulin resistance." (PMID 35789435, 2022). "Conversely, ablation of aCDase gene (encoding acidic ceramidase, ASAH1) led to ceramide accumulation in BAT, down-regulation of UCP1 protein, decline in energy expenditure, worsening of insulin resistance, and increase in fat accumulation." (PMID 33815291, 2021).
type 2 diabetes (5 papers, 2018 to 2024). "Under the condition of metabolic disorders, the activity of acid ceramidase or the expression level of Asah1 in type 2 diabetes is changed." (PMID 36407109, 2022). "In the case of metabolic disorders, there is either an alteration in acid ceramidase activity or a change in the expression level of ASAH1 in Alzheimer’s disease, cancer, and type 2 diabetes." (PMID 31817238, 2019).
Alzheimer disease (4 papers, 2018 to 2021). A progressive, neurodegenerative disease characterized by loss of function and death of nerve cells in several areas of the brain leading to loss of cognitive function such as memory and language. "Accordingly, failure to maintain these metabolites in balance was associated with several age-associated conditions including cancer and Alzheimer’s disease, making ASAH1 an attractive therapeutic target." (PMID 34102611, 2021). "ASAH1 catalyzes the conversion of ceramide into sphingosine and fatty acid and has been associated with pathologies such as Farber’s disease, Alzheimer’s disease, cancer, diabetes, and spinal muscular atrophy." (PMID 34102611, 2021).
diabetes (4 papers, 2018 to 2023). "Real-time PCR analysis demonstrated no changes in ASAH1 mRNA expression in diabetes vs. control placentae, suggesting that the increases in ASAH1 protein in diabetes are likely due to a reduced turnover of the enzyme." (PMID 36979912, 2023). "Expression of ASAH1, FES, and LRP4 was not affected by diabetes status." (PMID 32340285, 2020).
head and neck cancer (4 papers, 2017 to 2024). A primary or metastatic malignant neoplasm affecting the head and neck. "In head and neck cancer, inhibition of ASAH1 promoted cisplatin‐induced apoptosis in vitro and in vivo." (PMID 38924190, 2024).
lipogranulomatosis (4 papers, 2017 to 2023). "Farber’s lipogranulomatosis (or disease) is an extremely rare autosomal recessive LSD caused by mutations in the ASAH1 gene that expresses acid ceramidase." (PMID 33941173, 2021).
lymph node metastasis (3 papers, 2020 to 2024). "The expression of ASAH1 correlated with lymph node metastasis, suggesting that ASAH1 is a biomarker predictive of lymph node status." (PMID 32920549, 2020). "The results showed that CDC45 and CDT1 were highly expressed in the lymph node metastasis group, while ALDH1A1 and ASAH1 were downregulated." (PMID 38589907, 2024).
nephrotic syndrome (3 papers, 2022 to 2023). A collection of symptoms that include severe edema, proteinuria, and hypoalbuminemia; it is indicative of renal dysfunction. "Podocyte-specific deletion of acid ceramidase (Asah1) leads to an increase in ceramide levels in glomeruli of mice along with functional and morphological changes indicating the development of nephrotic syndrome." (PMID 35457062, 2022). "In addition to the effect of sphingosine/S1P alteration on podocyte function identified here, it was previously shown that the podocyte-specific depletion of acid ceramidase (ASAH1) in mice resulted in albuminuria and a nephrotic syndrome that is very reminiscent of the SPL knockout phenotype." (PMID 36834691, 2023). "Knockout of podocyte-specific aCDase gene, Asah1, in mice resulted in an increase in total and C16 ceramide levels in glomeruli, the main substrate of aCDase, leading to foot process effacement (FPE) in podocytes, massive proteinuria and albuminuria, suggestive of nephrotic syndrome (NS)." (PMID 35409370, 2022).
Obesity (3 papers, 2021 to 2023). Accumulation of substantial excess body fat. "In the present study, placental ASAH1 upregulation was most prominent in T2D, which shares pathogenesis with GDM and obesity." (PMID 36979912, 2023).
Parkinson disease (3 papers, 2023 to 2025). A progressive degenerative disorder of the central nervous system characterized by loss of dopamine producing neurons in the substantia nigra and the presence of Lewy bodies in the substantia nigra and locus coeruleus. "Within this group, sphingolipidoses genes involved in glycosphingolipid breakdown are known (GBA1) or candidate (SMPD1, ASAH1) risk factors for Parkinson’s Disease, though disease mechanisms remain unclear." (PMID 41279717, 2025). "The results showed that the expression levels of GLB1, ASAH1 and PSAP in the Parkinson’s disease (PD) group were significantly higher than those in the control group, which further supports our finding that these five small molecule RNA genes (SMRGs) may be biomarkers for Parkinson’s disease." (PMID 40534738, 2025).
preeclampsia (3 papers, 2018 to 2025). Preeclampsia is a hypertensive disorder of pregnancy that is characterized by new-onset hypertension with proteinuria presenting after 20 weeks of gestation, and depending on mild or severe forms may initially present with severe headache, visual disturbances, and hyperreflexia. "The hypoxic environment in placentae of Phd2−/− cKO mice also led to an increase in long-chain Cer content and decrease in ASAH1 expression, mimicking our reported findings for human preeclampsia." (PMID 41167398, 2025). "Similar observations regarding long-chain Cer accumulation and ASAH1 expression were made in the chronic hypoxic placentae of Phd2−/− cKO mice that mimics preeclampsia." (PMID 41167398, 2025). "In pregnancy, we characterized preeclampsia as a new ‘sphingolipid storage’ disorder as placentae from preeclamptic patients accumulate long-chain Cer due to diminished ASAH1 expression." (PMID 41167398, 2025). "Even in non-diabetic pregnancies, preeclampsia is characterized by hyperinsulinemia, and other features of the metabolic syndrome, and it is plausible that these metabolic characteristics in T2DPE could contribute to ASAH1 and SPHK upregulation." (PMID 36979912, 2023).
schizophrenia (3 papers, 2009 to 2025). A major psychotic disorder characterized by abnormalities in the perception or expression of reality. "That study found patients with schizophrenia had a higher abundance of ultra-rare variants, of which 7 SNPs loci were in the ASAH1 gene (rs781294134, rs759037498, rs761518207, rs13785393, rs764327759, rs757058563, and rs773025886)." (PMID 30029679, 2018). "Furthermore, this study identified two ASAH1 SNPs (rs7830490, and rs3753118) associated with schizophrenia." (PMID 30029679, 2018). "In the same year that the relationship between ASAH1 and SMA-PME was established, another report also demonstrated that Han Chinese patients diagnosed with schizophrenia showed a down-regulation of the ASAH1 gene." (PMID 30029679, 2018).
chronic obstructive pulmonary disease (2 papers, 2017 to 2023). A chronic and progressive lung disorder characterized by the loss of elasticity of the bronchial tree and the air sacs, destruction of the air sacs wall, thickening of the bronchial wall, and mucous accumulation in the bronchial tree. "In another study, gene expression profiling of PBMCs obtained from smokers exhibited a signature of chronic obstructive pulmonary disease (COPD) and emphysema characterized by multiple differentially regulation of genes FOXP1, TCF7, and ASAH1 involved in sphingolipid (ceramide) metabolism." (PMID 29376056, 2017).
gastric cancer (2 papers, 2021 to 2022). A primary or metastatic malignant neoplasm involving the stomach. "ASAH1 was used to build a risk model to reflect the dysregulated metabolic microenvironment in gastric cancer." (PMID 36147494, 2022). "In some cancers, such as gastric cancer, ASAH1 has also been shown to predict poor prognosis." (PMID 33766731, 2021).
glaucoma (2 papers, 2019 to 2024). Increased pressure in the eyeball due to obstruction of the outflow of aqueous humor. "In GAPDH normalized Western blots, we found elevated ASAH1 and ASAH2 levels in glaucoma." (PMID 31022733, 2019). "We found significant differences in glucosylsphingosine lipids, consistent with decreased GBA and GBA2 and increased ASAH1 and ASAH2 immunoreactivity in glaucoma, suggesting the potential impairment of sphingolipid enzymatic pathways in lysosomal and nonlysosomal cellular compartments." (PMID 31022733, 2019).
invasive ductal carcinoma (2 papers, 2020 to 2023). "Immunohistochemical staining was used to detect the expression of ASAH1 in 120 cases of non-special invasive ductal carcinoma (IDC-NOS)." (PMID 32920549, 2020).
lung adenocarcinoma (2 papers, 2020 to 2023). A carcinoma that arises from the lung and is characterized by the presence of malignant glandular epithelial cells. "Accordingly, lung adenocarcinoma patients were stratified as ASAH1+ (median > 4.643), ASAH1− (median < 4.643), STING+ (median > 2.767), and STING− (median < 2.767)." (PMID 37176007, 2023). "Results revealed that TAOK2 mRNA was down-regulated and ASAH1 mRNA was up-regulated in lung adenocarcinoma in male tumor tissue and female tumor tissue." (PMID 32236130, 2020). "As expected, in general, TAOK2 protein was suppressed and ASAH1 protein was increased in lung adenocarcinoma in male tumor tissue and female tumor tissue." (PMID 32236130, 2020). "To identify TAOK2 and ASAH1 expression difference in male and female tumor tissue in lung adenocarcinoma, we collected 8 pairs of tissues (tumor tissue and matched adjacent non-tumor tissue, 4 males and 4 females) by quantitative reverse transcription polymerase chain reaction (qRT-PCR)." (PMID 32236130, 2020).
prostate tumor (2 papers, 2013 to 2017). "ASAH1 has been shown to correlate with prostate tumor progression, and poor outcomes." (PMID 28445970, 2017).
steatosis (2 papers, 2020 to 2022). Increased lipid within the cytoplasm of cells. "In summary, we demonstrate that lysosomal ASAH1 overexpression improves alcohol-induced steatosis, lipid dysregulation, and oxidative stress via hepatic-specific ceramide reduction and that overexpression of this enzyme is relevant in human ALD." (PMID 32398264, 2020). "Enhanced lipophagy as a mechanism of steatosis attenuation upon induction of ASAH1 may relate uniquely to ALD." (PMID 32398264, 2020).
acute alcoholic hepatitis (1 paper, 2020). "ASAH1 is also upregulated in alcoholic cirrhotic and acute alcoholic hepatitis patients, perhaps as an attempt to reduce oxidative stress in ALD." (PMID 32398264, 2020).
acute pancreatitis (1 paper, 2022). An acute inflammatory process that leads to necrosis of the pancreatic parenchyma. "Cellular experiments showed that ASAH1 had the potential to be a risk factor for acute pancreatitis and that ASAH1 inhibition may be useful for acute pancreatitis treatment." (PMID 36068514, 2022). "In this research, the roles of ASAH1 in acute pancreatitis will be elucidated in pancreatic acinar cells and mouse." (PMID 36068514, 2022). "Consistent with the results in acinar cells, ASAH1 in the pancreas of mice with acute pancreatitis increased." (PMID 36068514, 2022). "Taken together, E3 ligase downregulation resulted in the inhibition of the proteasome degradation of ASAH1 in acute pancreatitis." (PMID 36068514, 2022). "To investigate the roles of ASAH1 in acute pancreatitis, we first detected the protein level of ASAH1 in pancreatic cells under the cerulein plus LPS treatment." (PMID 36068514, 2022). "MIB1/ASAH1/sphingosine/pyruvate kinase axis regulated trypsinogen activation in acute pancreatitis." (PMID 36068514, 2022). "ASAH1 could be increased in acute pancreatitis, indicating that this enzyme may influence the initiation of acute pancreatitis." (PMID 36068514, 2022). "Additionally, E3 ligase MIB1 decreased in acute pancreatitis, resulting in the inhibition of the proteasome degradation of ASAH1." (PMID 36068514, 2022). "Here we found that ASAH1 was involved in acute pancreatitis development, positively regulating trypsinogen, whereas premature trypsin could induce cell death eventually." (PMID 36068514, 2022). "Therefore, we next investigated the therapeutic potential of ASAH1 inhibitor, Ceranib-2, in acute pancreatitis." (PMID 36068514, 2022). "The results showed that ASAH1 increased in acute pancreatitis." (PMID 36068514, 2022). "In our research, ASAH1 was found to be increased in acute pancreatitis." (PMID 36068514, 2022). "ASAH1 may be the potential therapeutic target for acute pancreatitis." (PMID 36068514, 2022). "ASAH1 could be treated as a therapeutic target for acute pancreatitis." (PMID 36068514, 2022). "Thus ASAH1 may work with other proteins in cancer, which may be different in acute pancreatitis." (PMID 36068514, 2022). "In conclusion, during the process of acute pancreatitis, MIB1 downregulation led to ASAH1 upregulation, resulting in pyruvate kinase inhibition, followed by trypsinogen activation." (PMID 36068514, 2022). "Therefore, ASAH1 may regulate the location of cathepsin B in acute pancreatitis." (PMID 36068514, 2022). "Additionally, E3 ligase Mind bomb homolog 1 (MIB1) decreased in acute pancreatitis resulting in the decreased binding between MIB1 and ASAH1." (PMID 36068514, 2022). "Although cathepsin B is closely related to premature trypsinogen activation, the roles of ASAH1 in trypsinogen activation or acute pancreatitis are not fully understood." (PMID 36068514, 2022).
asthma (1 paper, 2024). "Among these genes, ASAH1, ACER3, and SGPP1 were identified as potential diagnostic biomarkers for asthma." (PMID 38297226, 2024). "The MCODE analysis identified a key module in the network, including three hub genes (ASAH1, ACER3 and SGPP1), all of which were downregulated genes and strongly linked to asthma." (PMID 38297226, 2024). "Moreover, ceramide metabolism could be a potential anti-rhinoviral target involved in acute worsening of asthma, and ceramide/sphingosine-1-phosphate imbalance was an underlying metabolic signature among asthmatic patients, indicating that ASAH1 may be involved in the pathogenesis of asthma." (PMID 38297226, 2024). "GSEA revealed that the role of ASAH1 in asthma may be closely related to protein secretion, adipogenesis, mTORC1 signaling, fatty acid metabolism, and E2F targets." (PMID 38297226, 2024). "ASAH1, ACER3 and SGPP1 might be diagnostic biomarkers for asthma, and are associated with increased immune system activation." (PMID 38297226, 2024). "Therefore, ASAH1 might be a potential novel biomarker to diagnose and treat asthma." (PMID 38297226, 2024). "Three downregulated LMRGs (ASAH1, ACER3 and SGPP1) were identified as hub genes for asthma, which were validated in GSE143192." (PMID 38297226, 2024). "The low expression of ASAH1 and SGPP1 in asthma was also validated in the GSE74075 dataset." (PMID 38297226, 2024). "Thus, we hypothesized that individuals with downregulated LMRGs (ASAH1, ACER3 and SGPP1) may be liable to mediate the immune response, and more easily develop asthma." (PMID 38297226, 2024). "Therefore, ASAH1 and SGPP1 may be the key genes involved in the occurrence of asthma." (PMID 38297226, 2024).
Ataxia (1 paper, 2020). Ataxia refers to impaired coordination of voluntary muscle movement. "Specifically, GBA2 is shown to interact with ASAH1 protein, which is over-expressed at the mRNA level in both neuronal “ataxia” datasets and peripheral blood “ataxia” datasets." (PMID 32937819, 2020).
colon adenocarcinoma (1 paper, 2019). "The acid ceramidase (ASAH1) inhibition has been shown to exert an anti-proliferative effect in colon adenocarcinoma cells." (PMID 31801289, 2019).
Dystonia (1 paper, 2025). An abnormally increased muscular tone that causes fixed abnormal postures. "Intragenic deletions and duplications can be found in the EPM2A and NHLRC1 (EPM2) genes, ASAH1 gene (SMA-PME), NUS1, and SGCE (myoclonus-dystonia)." (PMID 40584247, 2025).
endometrioid ovarian cancer (1 paper, 2021). "Interestingly, we recently showed that the expression of acid ceramidase (ASAH1), another key player in sphingolipid metabolism and signaling, was associated with significantly improved overall survival in estrogen receptor-negative endometrioid ovarian cancer." (PMID 33660008, 2021).
endometriosis (1 paper, 2022). The growth of functional endometrial tissue in anatomic sites outside the uterine body. "Our Western blotting results showed that the expression of ASAH1, Beclin1, and LAMP in the CC of the endometriosis group was higher than that of the control group." (PMID 35992117, 2022). "However, gene expression involved in ceramide synthesis (SPHK1, ASAH1, and SGPP1) and autophagy (BECN1, LAMP, and PC3) were significantly lower in MGCs with endometriosis, whereas CERS1 and UGCG expression increased." (PMID 35992117, 2022).
ependymal tumor (1 paper, 2020). A group of neoplasms which arise from the ependymal lining of the cerebral ventricles and from the remnants of the central canal of the spinal cord.
escherichia coli infection (1 paper, 2025). Infection with the organism Escherichia Coli. "ASAH1 was primarily enriched in the spliceosome pathway and also in the lysosome, regulation of actin cytoskeleton, chemokine signaling pathway, ribosome, junctional focal adhesion, and pathogenic Escherichia coli infection pathways." (PMID 40534738, 2025).
female infertility (1 paper, 2015). Diminished or absent ability of a female to achieve conception. "The same group has shown that knocking out Asah1 specifically in ovary caused apoptosis of oocytes, resulting in female infertility." (PMID 26474409, 2015).
food allergies (1 paper, 2024). "Second, four out of nine signature proteins downregulated in patients with AD and food allergies (i.e., Krt77, Asah1, Ggh, Cat) were significantly decreased in the RoraEKO epidermis vs. the control, indicating RORα could be critical for maintaining the expression levels of these important genes." (PMID 39409027, 2024).
gestational diabetes (1 paper, 2023). Carbohydrate intolerance first diagnosed during pregnancy. "In line with our observation of lower placental ceramide levels in both types of pre-gestational diabetes, immunoblotting for ASAH1, the enzyme that breaks down ceramide to sphingosine, revealed significantly greater levels of this enzyme in both T1D and T2D, compared to control pregnancies." (PMID 36979912, 2023).
hydrops (1 paper, 2023). "Here, we describe a case of ASAH1‐associated disease that presented as hydrops in the first trimester." (PMID 37962265, 2023).